PHF10 (PHD finger protein 10)
Description:
Involved in transcription activity regulation by chromatin remodeling. Belongs to the neural progenitors-specific chromatin remodeling complex (npBAF complex) and is required for the proliferation of neural progenitors. During neural development a switch from a stem/progenitor to a post-mitotic chromatin remodeling mechanism occurs as neurons exit the cell cycle and become committed to their adult state. The transition from proliferating neural stem/progenitor cells to post-mitotic neurons requires a switch in subunit composition of the npBAF and nBAF complexes. As neural progenitors exit mitosis and differentiate into neurons, npBAF complexes which contain ACTL6A/BAF53A and PHF10/BAF45A, are exchanged for homologous alternative ACTL6B/BAF53B and DPF1/BAF45B or DPF3/BAF45C subunits in neuron-specific complexes (nBAF). The npBAF complex is essential for the self-renewal/proliferative capacity of the multipotent neural stem cells. The nBAF complex along with CREST plays a role regulating the activity of genes essential for dendrite growth (By similarity).
Synonyms: BAF45a; FLJ10975; XAP135; SMARCG4
Tractability: Small molecule: a structure with a bound ligand is known. PROTAC: UniProt records ubiquitination sites on it; ubiquitination databases record sites on it; its protein half-life has been measured.
Gene: Protein-coding gene on chromosome 6 (169,703,902 to 169,725,566, reverse strand). Ensembl gene ENSG00000130024.
Subcellular location: Nucleus
Subcellular location (Human Protein Atlas): Nucleoplasm
Pathways (Reactome):
Chromatin organization: Formation of neuronal progenitor and neuronal BAF (npBAF and nBAF); Formation of the embryonic stem cell BAF (esBAF) complex; Formation of the polybromo-BAF (pBAF) complex
Gene Ontology:
Molecular function: chromatin binding; transcription coregulator activity
Biological process: chromatin remodeling; positive regulation of cell differentiation; positive regulation of double-strand break repair; positive regulation of myoblast differentiation; positive regulation of stem cell population maintenance; positive regulation of T cell differentiation; regulation of G0 to G1 transition; regulation of G1/S transition of mitotic cell cycle; regulation of mitotic metaphase/anaphase transition; regulation of nucleotide-excision repair; regulation of transcription by RNA polymerase II
Cellular component: nucleoplasm; chromatin; kinetochore; npBAF complex; nuclear matrix; RSC-type complex; SWI/SNF complex; nucleus
Genetic constraint (gnomAD): Loss-of-function variants: 14 observed, 23.53 expected, observed/expected ratio (o/e) 0.59, 90% interval 0.39 to 0.93. The upper end of that interval is the gene's LOEUF score, 0.93, which puts it in group 3 of 6, group 1 being the genes least tolerant of losing a copy. Missense variants: 203 observed, 263.72 expected, observed/expected ratio (o/e) 0.77, 90% interval 0.69 to 0.87. Synonymous variants: 94 observed, 86.81 expected, observed/expected ratio (o/e) 1.08, 90% interval 0.92 to 1.28.
Homologues: Orthologues: chimpanzee PHF10 (100% identical), macaque PHF10 (99% identical), mouse Phf10 (96% identical), guinea pig PHF10 (92% identical), rabbit PHF10 (91% identical), rat Phf10 (89% identical), pig PHF10 (81% identical), tropical clawed frog phf10 (80% identical), zebrafish phf10 (74% identical), Drosophila melanogaster e(y)3 (31% identical), Caenorhabditis elegans phf-10 (28% identical). Paralogues in human: KAT6A (22% identical), KAT6B (22% identical), RSF1 (20% identical), KAT5 (12% identical), KAT7 (12% identical), KAT8 (12% identical), DPF2 (7% identical), DPF3 (6% identical), DPF1 (6% identical).
Diseases named in the same sentence as PHF10 in open-access papers:
PHF10 is named in the same sentence as 20 diseases in open-access papers, as found by Europe PMC text mining. Sharing a sentence is not in itself a finding about the gene and the disease. The quoted sentences say what the papers report.
gastric cancer (5 papers, 2015 to 2025). A primary or metastatic malignant neoplasm involving the stomach. "miR-409-3p also suppresses the migration and invasion of bladder cancer T24 and 5,637 cells via targeting c-Met and regulates cell proliferation and apoptosis by targeting PHF10 in SGC-7901 gastric cancer cells." (PMID 25880988, 2015). "In addition, miR-409-3p is downregulated and capable of suppressing proliferation, invasion, survival, and metastasis by regulating the level of radixin and PHD finger protein 10 (PHF10) in gastric cancer." (PMID 35055115, 2022). "have found that circ_0001023 promotes the progression of gastric cancer (GC) through modulating the miR‐409‐3p/PHF10 axis, suggesting that PHF10 is an oncogene in GC." (PMID 39904827, 2025). "What’s more, our team has been worked on some of the differential genes such as PHF10, CEACAM6, SFRP1, SOX11, CLDN1 to investigate their expression and functions in gastric cancer and the results perfect proved our microarray data." (PMID 25928635, 2015).
breast carcinoma (4 papers, 2016 to 2021). "In this analysis, we found the upregulation of PHF10 expression in three different cancer types, including colorectal cancer, GC, and leukemia, and downregulation of PHF10 in breast cancer." (PMID 33912555, 2021). "Furthermore, there have been no reports on the activity of CLIP4, CAPN2, CRLF1, CYBRD1, PHF10, and TRHDE in breast cancer or chemoresistance, thus making them new candidates for understanding breast cancer, the EMT, and chemoresistance." (PMID 27094684, 2016).
pancreatic cancer (2 papers, 2021 to 2024). "In terms of the expression level of PHF10 protein, pancreatic cancer showed a low positive rate, ranking seventh from the bottom among 43 common cancer types." (PMID 35127503, 2021). "Based on GSE15471 analysis, the expression of PHF10 in pancreatic cancer tissues was significantly higher than that in normal tissues." (PMID 35127503, 2021). "In this study, the expression of PHF10 varied significantly among the five immune subtypes in pancreatic cancer." (PMID 35127503, 2021). "Third, the prognostic efficacy of LINC00242 and PHF10 and their regulatory relationship should be verified in more pancreatic cancer datasets." (PMID 35127503, 2021). "Then, we further analyzed the expression of PHF10 in pancreatic cancer and its prognostic value." (PMID 35127503, 2021). "Furthermore, we used external experiments to further study the regulatory relationship between LINC00242 and PHF10 in pancreatic cancer cell lines." (PMID 35127503, 2021). "For example, ZC3H13 mediates m6A modification of CENPK mRNA to increase translation of PHF10 in a YTHDF1-dependent manner, which in turn inhibits pancreatic cancer." (PMID 38351022, 2024).
cutaneous melanoma (1 paper, 2022). A primary melanoma arising from atypical melanocytes in the skin. "It has been reported that PHF10 is over-expressed in cutaneous melanoma and interacts with MYC, to recruit the PBAF complex to pro-proliferative loci, and promote cell cycle progression." (PMID 35323214, 2022). "We found that PHF10 is not as frequently mutated as other PBAF components in cutaneous melanoma." (PMID 35323214, 2022).
gastric intestinal type adenocarcinoma (1 paper, 2021). An adenocarcinoma of the stomach arising on a background of intestinal metaplasia. "In a detail, we analyzed PHF10 expression in GC as compared to tissue for gastric mixed adenocarcinoma and gastric intestinal type adenocarcinoma." (PMID 33912555, 2021).
head and neck squamous cell carcinoma (1 paper, 2020). A squamous cell carcinoma that arises from any of the following anatomic sites: lip and oral cavity, nasal cavity, paranasal sinuses, pharynx, larynx, and salivary glands. "However, the PHF10 subunit found to have a negative coexpression correlation in Head and Neck Squamous Cell Carcinoma." (PMID 31932624, 2020).
lentivirus infection (1 paper, 2025). Virus diseases caused by the Lentivirus genus. "To explore the regulatory role of PHF10 on CHOL cells, we first established GFP‐tagged PHF10‐overexpressing HuCCT1 and RBE cells via lentivirus infection technology." (PMID 39904827, 2025).
renal carcinoma (1 paper, 2020). A carcinoma arising from the epithelium of the renal parenchyma or the renal pelvis. "Decreased PHF10 expression in patients with renal cancer correlates with ahigher chance of patient survival, which may be related to thepositive effect of the c-MYC oncogene on PHF10 expression." (PMID 33456978, 2020).
schwannomatosis (1 paper, 2015). The least frequent form of the rare genetic disorder neurofibromatosis. "Here, we show that mutations in INI1 that cause schwannomatosis target a hitherto unidentified N-terminal winged helix DNA binding domain that is also present in the BAF45a/PHF10 subunit of the SWI/SNF complex." (PMID 26073604, 2015).
cancer (5 papers, 2012 to 2025). A tumor composed of atypical neoplastic, often pleomorphic cells that invade other tissues. "We found that the mRNA level of PHF10 was significantly associated with the immune infiltration in various types of cancer." (PMID 35127503, 2021). "PHF10 expression was found to be significantly correlated with the immune cell infiltration and immune subtype across many cancer types." (PMID 35127503, 2021). "We then used the UALCAN database to analyze the expression levels of the PHF10 signature in 24 types of cancers and normal tissues." (PMID 33912555, 2021). "For individual cancer stages, we observed the highest expression level of PHF10 in patients with stage 3." (PMID 33912555, 2021). "Based on web tool TIMER, we further examined PHF10 expression in multiple human cancers with RNA-seq data from the TCGA database." (PMID 35127503, 2021). "ONCOMINE compares the difference in expression level between the cancer tissue and normal tissue depending on the numbers of significant unique analyses, which represents the differences in PHF10 mRNA expression." (PMID 33912555, 2021). "Next, we investigated the correlations between PHF10 expression and immune subtypes in human pan-cancer." (PMID 35127503, 2021). "In the current study, pan-cancer analysis demonstrated that LINC00242 and PHF10 co-expressed in many types of cancer." (PMID 35127503, 2021). "To explore the expression pattern of the final PHF10 signature, we went through comparative expression analysis of PHF10 between different cancer and normal tissues using an online web-server, such as ONCOMINE and UALCAN." (PMID 33912555, 2021). "Different important target genes have been validated in different cancers, such as the transcriptional regulator PHF10, the pro-metastatic gene radixin, the pro-angiogenic gene angiogenin (ANG), the oncoprotein GAB1 and the pro-metastatic gene c-Met." (PMID 27057640, 2016). "Additionally, the web tool TIMER was used to detect the distribution and expression of PHF10 in pan-cancer." (PMID 35127503, 2021). "PHF10 was upregulated and downregulated in 12 different cancers, respectively." (PMID 33912555, 2021). "In addition, we found a significant co-expression correlation between LINC00242 and its target gene PHF10 in multiple cancer types, including PAAD, KIRC, ACC, TGCT, UVM, LIHC, and UCS (p < 0.01)." (PMID 35127503, 2021). "Additionally, the PHF10 mRNA level in PAAD samples was relatively low among 17 cancer types; However, the expression of PHF10 was significantly upregulated in PAAD compared with normal tissues." (PMID 35127503, 2021). "The pan-cancer results further confirmed that there was a significant correlation between PHF10 and immunophenotype, indicating that PHF10 may have potential value in immunotherapy." (PMID 35127503, 2021). "Moreover, we further investigated the relationship between PHF10 and immune infiltration in human pan-cancer." (PMID 35127503, 2021). "Additionally, the web tool Tumor Immune Estimation Resource (TIMER) was used to study the expression level of PHF10 in pan-cancer." (PMID 35127503, 2021). "Interestingly, the PHF10 expression level varied significantly among different cancer types." (PMID 35127503, 2021). "Compared with control cell, PHF10‐deleted HuCCT1 and RBE cells further exhibited enhanced cancer stem cell (CSC)‐like properties, like self‐renewal ability." (PMID 39904827, 2025). "PHF10 is a target gene of LINC00242 and has been shown to co-express with LINC00242 in a variety of cancers." (PMID 35127503, 2021). "We demonstrate here that the paralogous cancer-related minor SWI/SNF subunits DPF1, -2, -3; BCL7A, -B, -C; and SS18 and SS18L1 reside in BAF-class human SWI/SNF complexes and, that PHF10 marks PBAF SWI/SNF complexes." (PMID 22442726, 2012). "However, the function of LINC00242 and PHF10 in human pan-cancer is not clear." (PMID 35127503, 2021).
Tumor (3 papers, 2021 to 2025). "In order to evaluate the effect of PHF10 on the tumor microenvironment, we analyzed the tumor-infiltrating immune cells (TIICs) associated with PHF10 expression by CIBERSORT on the basis of TCGA cohort." (PMID 35127503, 2021). "Collectively, our data supported that PHF10 may be a tumour suppressor and PHF10 deficiency may notably enhance tumour proliferation, migration, self‐renewal ability, as well as chemotherapy resistance." (PMID 39904827, 2025). "However, high‐throughput sequencing data implicated that downregulation of PHF10 in uveal melanoma cell lines and tumours altered a number of biological pathways associated with development and adhesion." (PMID 39904827, 2025). "Low PHF10 expressions were also associated with advanced tumour grades of CHOL." (PMID 39904827, 2025). "Our study thus implicated that PHF10 might be a tumour suppressor in CHOL proliferation and metastasis, highlighting a potential therapeutical target for CHOL treatment." (PMID 39904827, 2025). "Collectively, this study demonstrated that PHF10 functions as a tumour suppressor in CHOL, and is a novel target to predict and overcome chemoresistance." (PMID 39904827, 2025). "Besides, we are still uncertain about the underlying mechanisms between PHF10 and immune infiltrations of CHOL tumour microenvironment." (PMID 39904827, 2025). "The subcutaneous CHOL tumour models also indicated that PHF10 ablation could potentiate in vivo tumour growth of CHOL cells." (PMID 39904827, 2025). "Last of all, we also performed the subcutaneous tumour model and found that targeting HMGB1 could suppress the in vivo growth of tumours derived from the PHF10‐deleted cells, as evidenced by the quantification of tumour growth curve and tumour weight." (PMID 39904827, 2025). "Overall, these findings strongly suggest that PHF10 plays an important role in tumor immunity." (PMID 35127503, 2021). "PHF10, one subunit of SWI/SNF complex, expressed highly in tumours that correlated with tumorigenesis." (PMID 39904827, 2025). "In line with in vitro findings, Glycyrrhizin(20 μM) was effective to inhibit the growth of in vivo tumours derived from PHF10‐deleted CHOL cells, as reflected by tumour volumes, Ki‐67 and CD31 staining levels." (PMID 39904827, 2025). "In addition, in consistent with the results, the colony formation ability, migration ability, as well as self‐renewal ability were enhanced with PHF10 depletion, whereas HMGB1 knockdown impaired these tumour‐promoting properities." (PMID 39904827, 2025).
PHF10 also shares sentences with these, for which no sentence is quoted: pancreatic adenocarcinoma (2 papers); bladder cancer (1); cholangiocarcinoma (1); Colon cancer (1); colorectal cancer (1); glioblastoma (1); leukemia (1); lung carcinoma (1); periventricular nodular heterotopia (1).